MIR1205 (microRNA 1205)
Synonyms: hsa-mir-1205; MIRN1205
Gene: MicroRNA gene on chromosome 8 (127,960,633 to 127,960,695, forward strand). Ensembl gene ENSG00000221771.
Homologues: Orthologues: chimpanzee ptr-mir-1205 (100% identical).